WNT5A (Wnt family member 5A)
Diseases named in the same sentence as WNT5A in open-access papers (continued):
Sharing a sentence is not in itself a finding about the gene and the disease.
tumor (continued). "It is associated with various neoplasms produced by WNT pathway deregulation; WNT5A, a member of the WNT family, has been linked to carcinogenesis, exhibiting either oncogenic or tumor-suppressive effects." (PMID 39176352, 2024). "The specific effects of WNT5A can be both tumor-suppressive and tumor-promoting, highlighting the need for a deeper understanding of the complex role of this signaling pathway in cancer." (PMID 39176352, 2024). "Wnt5a exerts its tumor suppressor effect in many ways but typically has the same outcome, which is the repression of the Wnt/β-catenin pathway." (PMID 39123414, 2024). "Our qRT-PCR result showed that HK2 mRNA expression was upregulated in GC tumor tissues and positively correlated WNT5A expression." (PMID 39054546, 2024). "Wnt5a is believed to function as a tumor suppressor in CRC by inhibiting the Wnt/β-catenin signaling pathway." (PMID 39200196, 2024). "In diverse TCGA tumor types, the OS time was compared to tumors with higher and lower levels of WNT5A expression." (PMID 39176352, 2024). "As there is no consensus on what constitutes normal, low, or high levels of WNT5A genes, we have provided this figure to depict a comparison across various tumor types." (PMID 38558536, 2024). "In the TME, tumor-derived exosomes carrying fatty acids or tumor cells use the paracrine Wnt5a/b-catenin signaling pathway to activate peroxisome proliferator-activated receptors in DC cells, leading to enhanced FAO." (PMID 39464876, 2024). "WNT5A, one member of the WNT family, has been linked to carcinogenesis, displaying either oncogenic or tumor-suppressive properties." (PMID 39176352, 2024). "Comparisons were made between tumors' OS time with higher and lower levels of WNT5A expression in various TCGA tumor types." (PMID 39176352, 2024). "Reports have shown that WNT5A has both oncogenic functions and tumor-suppressive functions in different cancers." (PMID 37173306, 2023). "This was accompanied by an elevation of CD8+-T cells and M1 TAM, as well a decrease of FOXP3+-Treg cells and M2 TAM in the tumor tissues, implying that WNT5A modulates the immune response to the tumor in a tolerogenic fashion." (PMID 36982422, 2023). "And WNT5A was involved in the angiogenesis of myocardial injury in diabetic mice and tumor development." (PMID 37396938, 2023). "CAFs in colorectal, endometrial, and oesophageal cancers contribute to the secretion of Wnt5a, Wnt1, Wnt10b, and Wnt2, further promoting tumour proliferation, migration and relapse by activating canonical/noncanonical Wnt pathways." (PMID 38136392, 2023). "Immunohistochemical analysis of 38 iCCA cases detected Wnt3a protein in the cytoplasm of tumor cells in 92.1% of cases, Wnt5a in 76.3% of cases, and Wnt7b in all tumors." (PMID 37190050, 2023). "WNT5A knockout mice achieved by crossing WNT5A‐floxed mice (Wnt5afl/fl) with UBC‐Cre/ERT2 mice were distinguished from the control tumor group at the cytokine level, including cytokines that regulate immune cell chemotaxis." (PMID 37605299, 2023). "WNT5A has been found to induce tumor suppression and function as an oncogene depending on the specific cancer type." (PMID 37368072, 2023). "WNT5A expression is associated with several cancers, resulting in constitutive activation of ROR2-mediated signaling and contributing to tumor progression (7, –9)." (PMID 37722040, 2023). "Others have shown that an induced overexpression of WNT5A in vitro led to tumour suppressive responses characterised by impaired migration and invasion." (PMID 36347335, 2023). "Immunofluorescence staining also showed that the expression of TCAF2 and Wnt5a in NG2+ TPCs was significantly increased in primary tumor tissues derived from CRC patients with liver metastasis compared with those without liver metastasis." (PMID 37635201, 2023). "Wnt5a is an important member of the Wnt pathway and acts as either tumor-suppressive or tumor-promoting in different cancer types." (PMID 40226410, 2023).
tumor (continued). "The Wnt5a/Ror2 signaling promotes cell migration and tumor invasion through up-regulation of metalloproteases in epidermoid carcinoma cells." (PMID 36675086, 2023). "The analysis of 48 cases of liver fluke-derived iCCA showed that mRNA levels of Wnt3a, Wnt5a, and Wnt7b were higher in the tumor tissue than in the surrounding liver tissue." (PMID 37190050, 2023). "Wnt5a expression was also enriched in OC samples and was found in the OC tumor microenvironment of visceral adipose cells, whereas ROR1 expression was detected in human adipose cells." (PMID 37400436, 2023). "On the other hand, the M13HS-2 and -8 tumor hybrids lack expression of the active form of WNT5A, which has been suggested as a M state marker." (PMID 38139138, 2023). "Upregulated ROR2 and Wnt5a have shown to represent poor tumor stage and lymphatic metastasis in LSCC, suggesting that ROR2 was an independent prognostic factor." (PMID 36923505, 2023). "In turn, these stromal cells secrete Wnt ligands like Wnt3a, Wnt5a, and Wnt7b, and other factors that further activate Wnt signaling in tumor cells, creating a positive feedback loop that promotes tumor growth and progression." (PMID 37760801, 2023). "In order to further prove that NE can regulate the expression level of WNT7A, we detected the expression levels of Wnt1, Wnt2, Wnt3a, Wnt4, Wnt5a, Wnt6, Wnt7a and Wnt10a in tumour tissues of anti-PD-1 mAb + Vehicle and NE + anti-PD-1 mAb + Vehicle groups." (PMID 36646807, 2023). "On the contrary, Wnt-5a was reported to act as a tumor suppressor in neuroblastoma and colon cancer." (PMID 37237541, 2023). "Secondly, secreted WNTs, especially WNT5A, were reported to be involved in M2 polarization of TAMs, leading to an altered cytokine profile and immune cell exclusion from the tumor." (PMID 36982422, 2023). "Immunofluorescence staining showed that knocking-‍out Wnt5a in tumor reduced stromal Lin28b expression in orthotopic models." (PMID 37898598, 2023). "Insights from this research will likely address controversies regarding the tumor-suppressive or -promoting function of specific WNTs, such as WNT5A." (PMID 36982422, 2023). "Paracrine signaling, mediated for instance by WNT5A, is important for tumor immune evasion, which can be observed across many different cancer entities." (PMID 36982422, 2023). "In contrast, in the irradiation group, the over-expressed WNT5a tumor grew faster and showed resistance to radiation." (PMID 35517407, 2022). "Based on these results, the tumor-suppressing or tumor-stimulating effects of WNT5A depend on the cancer type and stage." (PMID 35595735, 2022). "In conclusion, our studies first confirmed that WNT5A functioned as a tumor promoter by enhancing ESCC cell metastasis." (PMID 35595735, 2022). "The bone marrow of patients with low levels of ROR2 disrupted Wnt5a signalling produced by the osteoblastic niche, which hinted at the potential development of osteolytic tumours in bone." (PMID 36307871, 2022). "WNT5A overexpression induced the EMT by upregulating SNAIL expression and downregulating E-cadherin, which was associated with tumor invasion and metastasis." (PMID 35595735, 2022). "Genes in the Wnt signaling pathway such as, WNT2 and WNT5A, were upregulated in tumor fibroblasts while SFRP1, an inhibitor of Wnt signaling was downregulated." (PMID 35999201, 2022). "Aberrant activation or inhibition of WNT5A signaling exerts both oncogenic and tumor suppressive effects." (PMID 36476423, 2022). "The role of WNT5A in promoting tumor metastasis was further confirmed in a nude mouse lung metastasis assay." (PMID 35595735, 2022). "The WNT5A protein level was detected using IHC staining in a tissue microarray containing 145 paired ESCC tumor-normal tissues." (PMID 35595735, 2022). "Wnt ligands that were expressed in both tumor cohorts included Wnt5a, Wnt5b, and Wnt7b foremost, in accordance with the reported expression of these ligands in mammary epithelium." (PMID 36106661, 2022).
tumor (continued). "Our studies here support Wnt5a as a potential paracrine driver of tumor progression in response to a high-fat diet." (PMID 35884514, 2022). "We found that an anti-Wnt5a peptide and ephrinA1-Fc have the potential to effectively antagonize GSCs’ tumor propagating and invasive ability in vitro, substantially increasing survival in vivo, when used alone." (PMID 35414102, 2022). "The IL-6 target genes MET, IGF1, MMP3, CEACAM1, MMP1 and WNT5A were upregulated, which enabled the tumour cells to become invasive." (PMID 35022523, 2022). "Among the second category, the role of the Wnt5a/NF-κB has been particularly investigated in the context of studies on tumor microenvironment, revealing how an aberrant expression of Wnt5a is immunosuppressive." (PMID 35873564, 2022). "Single-cell analysis of human basal cell carcinoma shows a WNT5A reactive stroma that promotes tumor HSP70 to maintain growth." (PMID 35687691, 2022). "For example, WNT5a induces the expression of Il12 in dendritic cells, which results in the suppression of myeloid-derived suppressor cells and tumor progression." (PMID 36612190, 2022). "Abnormal activation or inhibition of Wnt5a is an important marker of tumor progression 9, 10, play the role of antitumor effect in thyroid cancer 11 and breast cancer." (PMID 35517407, 2022). "The signaling relationships between BCC epithelial cells and FIBs revealed a WNT5A-mediated inflammatory signature that led to the discovery of an HSP-specific protective mechanism that is necessary to maintain tumor growth." (PMID 35687691, 2022). "Through the Comparative Toxicogenomics Database—CTD database—among the 15 EMT genes described, four genes (MMP2, MAP1B, SNAI2, and WNT5A) were related to neoplasms and brain disorders, named neuronal EMT-related genes." (PMID 36553576, 2022). "To further verify our findings, we constructed a nude-mouse transplanted tumor model and administered 4Gy of irradiation on the 11th and 12th day after planting 6-10B cells with control and Wnt5a-overexpression." (PMID 35517407, 2022). "As for CRC, WNT5A is expressed primarily in tumor matrix, especially in TAMs, but its specific biological function and related mechanism are not fully understood, which needs further exploration." (PMID 35186730, 2022). "Other studies indicated that Wnt5a expression in the circulating tumor cells of patients with metastatic castration-resistant PCa was a negative indicator of overall survival." (PMID 35884514, 2022). "It is known that tumor-derived exosomes mediate important roles in tumor progression; in fact, a pro-tumoral role of exosomal WNT5A has been reported in several cancers." (PMID 35742983, 2022). "In the lung, WNT5A is overexpressed, correlating with tumor aggressiveness, lower survival, and the development of resistance to therapy." (PMID 35742983, 2022). "In line with this, findings of a study showed that Wnt5a expressed by TAMs stimulate tumor cell proliferation and migration of CRC cells, including HCT116 and DLD1, and recruited macrophage infiltration through enhancing the CaMKǀǀ-ERK signaling pathway." (PMID 34603445, 2021). "WNT5A exerts both tumor-suppressing and oncogenic effects depending on the type and location of cancer." (PMID 33799999, 2021). "Rather, WNT-5A knockdown increased the expression of genes involved in extracellular matrix remodeling and communication with inmune cells, suggesting that WNT-5A modulates the MPNST microenvironment thereby inhibiting tumor formation." (PMID 34771683, 2021). "In detail, upon the co-culture with adipocytes, tumor cells increased early the expression of WNT5A that activates c-Jun and AP1 in adipocytes." (PMID 33917351, 2021). "Another study indicated that it activates the Wnt/β-catenin pathway to regulate tumor proliferation and migration via miR-3924/WNT5A." (PMID 34568075, 2021).
tumor (continued). "Another study revealed that Wnt5a in breast CAFs was significantly downregulated after 1,25D (1alpha, 25 dihydroxyvitamin D3) treatment 49, in which 1,25D elicited obvious tumor suppressive effects." (PMID 33754039, 2021). "ZEB1 also can activate signaling pathways associated with tumor metastasis, including PI3K/AKT and WNT5a." (PMID 34916487, 2021). "The presence of DCA promotes Egfr, Wnt5a, and Rela overexpression, and a significant downregulation of “tumor suppressor” miR-451a." (PMID 33670587, 2021). "WNT5a has dual effects on the tumor microenvironment; it can activate the autocrine ROR1/Akt/P65 pathway and promote immune cell inflammation and chemotaxis." (PMID 34565373, 2021). "According to the results of the previous study, the autocrine effect of Wnt5a on TAMs leads to the promotion of CRC tumor growth." (PMID 34603445, 2021). "Based on the findings of recent studies and the available evidence on the suppressive effect of Wnt5a on types of cell lines and tumor tissue of CRC, this protein can be considered a key therapeutic target in inhibition of CRC progression." (PMID 34603445, 2021). "As a result, the total WNT5A mRNA expression increased more than 100-fold in the acute-type ATL tumor cells compared to the carrier HTLV-1 infected cells and smoldering-type ATL cells." (PMID 33603066, 2021). "It has been demonstrated that ectopic expression of Wnt5a in methylation-stimulated silencing Wnt5a CRC cells inhibits tumor cell clonogenicity via downregulation of β-catenin protein levels and inactivation of Wnt β-catenin signaling." (PMID 34603445, 2021). "In anti-PD-1 treated solid tumor murine models, activated CD8+ T cells induced NLRP3 inflammasome activation within tumor cells, which resulted in downstream Wnt5a-mediated CXCR2 ligand expression and MDSC recruitment into the tumor tissue." (PMID 33572196, 2021). "Wnt5A secreted from tumor cells promotes the differentiation of naïve Mφ into M1φ, whereas it inhibits the differentiation into M2 type and T cell activation." (PMID 34319035, 2021). "CXCL12 and Wnt5a were expressed in the cytoplasm of tumor-adjacent fibroblasts and the GC cells, respectively." (PMID 33854601, 2021). "Tumor‐derived protein derived from Wnt5A gene (WNT5A) plays an important role in primary and metastatic PCa." (PMID 33639039, 2021). "Overexpression of Wnt5a has been reported to promote the invasive and metastatic characters of tumor cells." (PMID 33603066, 2021). "In the circ0101675 knockdown group, the WNT3A and WNT5A expression was significantly reduced in tumor tissues." (PMID 34093821, 2021). "In MCF-7 cell supernatants, it has been observed that microvesicles and exosomes occur with the ability to induce overexpression of Wnt5a in TAMs and transfer it to tumor cells, to improve their invasiveness." (PMID 33671415, 2021). "CSF3 also correlated strongly with WNT5a expression, which can promote or inhibit tumor growth dependent on its isoform." (PMID 33606788, 2021). "As stWNT5A correlated positively with tumor‐derived WNT5A, the communication mechanisms of stWNT5A were also addressed in our study." (PMID 33639039, 2021). "In conclusion, stWNT5A appears to play a role in dissemination of PCa to other tissues and acts in a different way than tumor‐derived WNT5A." (PMID 33639039, 2021). "Regarding the oncogenic effect of Wnt5a, this protein can potentially be influenced on CRC cells mediated by specific cells, including tumor-associated macrophages (TAMs)." (PMID 34603445, 2021). "The FOSL2 protein levels in tumor tissues were closely related to the Wnt5a concentration in tumor extracts." (PMID 33754039, 2021). "WNT5A is known to inhibit the proliferation of lymphatic B‐cells and has a function as a tumor suppressor in hematopoietic tissue." (PMID 33639039, 2021).
tumor (continued). "In contrast to this result, abnormal levels of Wnt5a methylation-induced loss of Wnt5a expression significantly correlates with the presence of the lymph node and advanced TNM stage, suggesting that Wnt5a acts as a tumor suppressor gene in patients with CRC." (PMID 34603445, 2021). "Using CCK8 assay, and we then tested cell viability and found that both application of miR-1270/miR-545 inhibitors and WNT5A overexpression significantly increase the tumor progression in sh-circZFR BCa cells." (PMID 33928018, 2020). "For example, Wnt5a antagonizes canonical Wnt/β-Catenin signaling and exhibits tumor-suppressive activity in some circumstances, but other studies have reported that Wnt5a controls both canonical and noncanonical Wnt signaling." (PMID 33234169, 2020). "MicroRNAs (miRNAs) including miR-30a and miR-129-5p has been documented to function as tumor suppressors by targeting WNT5A." (PMID 32181818, 2020). "For example, tumor cells use paracrine Wnt5a/β-catenin signaling to activate PPARγ in DCs, leading to enhanced FAO and DC dysfunction." (PMID 33086073, 2020). "Knocking down Wnt5a mostly impaired the pro-tumor effect of TAMs, which revealed that TAMs depended on Wnt5a for their cancer-promoting roles." (PMID 32228612, 2020). "Subsequently, we found that Wnt5a+ TAMs facilitated tumor cell proliferation and migration, and recruited macrophages infiltration." (PMID 32140070, 2020). "In EOC cell lines and tumors, WNT5A overexpression induces cellular senescence, a tumor-suppressive pathway, and antagonizes the β-catenin-dependent transcriptional activity." (PMID 32560059, 2020). "Clone formation and transwell assays were performed to determine the effects of Wnt5a–treated macrophages on tumor proliferation, migration and invasion in vitro." (PMID 32228612, 2020). "The aberrant activation or inhibition of Wnt5a signaling is emerging as an important event in tumorigenesis, exerting both oncogenic and tumor suppressive effects in cancer." (PMID 32650388, 2020). "The tumor-promoting functions of Wnt5a in TAMs depended on CaMKII-ERK pathway-mediated CCL2 secretion." (PMID 32140070, 2020). "Knockdown of either Wnt5a or ALCAM inhibited tumour cell migration, confirming the role of the Wnt5a/ALCAM axis in the migratory phenotype of ER-positive BC." (PMID 33080952, 2020). "Mechanistically, pro-tumor functions of Wnt5a in TAMs depended on CaMKII-ERK pathway-mediated CCL2 secretion." (PMID 32140070, 2020). "Collectively, our data suggest that both in AB cells or tumor tissues, Wnt5a can regulate dynamics changes of mitochondria." (PMID 32742496, 2020). "Mechanistically, the pro-tumor effects of Wnt5a in TAMs were dependent on CaMKII-ERK pathway-mediated CCL2 production." (PMID 32140070, 2020). "Further correlation analysis and luciferase assay also verified that miR-1270/miR-545 directly target WNT5A and inhibit tumor progression in BCa." (PMID 33928018, 2020). "In terms of cytokines, here we demonstrated that Wnt5a stimulated macrophages to produce IL-10, which in turn induced M2 polarization of macrophages, finally facilitating tumor growth, invasion and metastasis." (PMID 32228612, 2020). "The expression of Wnt5a was negatively correlated with the degree of tumor differentiation and the aggressive behavior." (PMID 32923386, 2020). "We then treated CRC cells directly with human recombinant protein Wnt5a and observed the direct effect of Wnt5a on tumor cells." (PMID 32140070, 2020). "Wnt5a knockdown mostly reduced the cancer-promoting functions of TAMs, showing that TAMs were dependent on Wnt5a for their pro-tumor roles." (PMID 32140070, 2020). "We propose that WNT5A is an important component of ascites, the tumor microenvironment that in turn helps to spread these pro-metastatic factors." (PMID 31903136, 2020). "In pancreatic cancer and human urothelial carcinoma, Wnt5a/ROR2 signaling is associated with EMT and promotes tumor cell invasion and metastasis." (PMID 32848510, 2020).